ZNF492 (zinc finger protein 492)
Description:
May be involved in transcriptional regulation.
Synonyms: KIAA1473; ZNF115
Tractability: PROTAC: ubiquitination databases record sites on it.
Gene: Protein-coding gene on chromosome 19 (22,634,324 to 22,667,671, forward strand). Ensembl gene ENSG00000229676.
Subcellular location: Nucleus
Pathways (Reactome):
Gene expression (Transcription): Generic Transcription Pathway
Gene Ontology:
Molecular function: DNA-binding transcription factor activity, RNA polymerase II-specific; RNA polymerase II cis-regulatory region sequence-specific DNA binding; DNA-binding transcription repressor activity, RNA polymerase II-specific
Biological process: regulation of DNA-templated transcription; negative regulation of transcription by RNA polymerase II; regulation of transcription by RNA polymerase II
Cellular component: nucleus
Genetic constraint (gnomAD): Loss-of-function variants: 3 observed, 6.14 expected, observed/expected ratio (o/e) 0.49, 90% interval 0.22 to 1.25. That is too few expected variants to judge how well the gene tolerates losing a copy. Missense variants: 352 observed, 491.57 expected, observed/expected ratio (o/e) 0.72, 90% interval 0.65 to 0.78. Synonymous variants: 110 observed, 165.09 expected, observed/expected ratio (o/e) 0.67, 90% interval 0.57 to 0.78.
Homologues: Paralogues in human: ZNF254 (72% identical), ZNF726 (71% identical), ZNF708 (69% identical), ZNF728 (69% identical), ZNF676 (69% identical), ZNF724 (68% identical), ZNF681 (66% identical), ZNF714 (66% identical), ZNF493 (65% identical), ZNF429 (65% identical), ZNF85 (65% identical), ZNF93 (64% identical), and 164 more.
Diseases named in the same sentence as ZNF492 in open-access papers:
ZNF492 is named in the same sentence as 3 diseases in open-access papers, as found by Europe PMC text mining. Sharing a sentence is not in itself a finding about the gene and the disease. The quoted sentences say what the papers report.
leukemia (1 paper, 2021). A malignant (clonal) hematologic disorder, involving hematopoietic stem cells and characterized by the presence of primitive or atypical myeloid or lymphoid cells in the bone marrow and the blood. "Among the other genes with strong correlations between DNA methylation and gene expression, aberrant DNA methylation and downregulation of FKBP9, CA8, MSC, TRPC6, ZNF492, ZNF229, and ZNF471 genes in leukemia patients are reported here for the first time." (PMID 34575904, 2021).
ZNF492 also shares sentences with these, for which no sentence is quoted: liver cancer (1 paper); type-2 diabetes (1).